LEP (leptin)
Diseases named in the same sentence as LEP in open-access papers (continued):
Sharing a sentence is not in itself a finding about the gene and the disease.
Obesity (continued). "Obesity is also associated with other inflammatory autoimmune diseases, such as ulcerative colitis, Crohn’s disease and psoriasis, and increased leptin expression has also been reported in Behcet ́s disease, psoriasis, thyroiditis and during the acute phase of ulcerative colitis." (PMID 32824322, 2020). "Adiponectin and leptin levels are known to be significantly associated with obesity." (PMID 32397260, 2020). "Resistance to leptin is considered a hallmark of obesity and has been shown to lead to hepatic IR." (PMID 32911852, 2020). "Moreover, since plasma leptin levels are positively correlated with body mass index (BMI) and obesity is a risk factor for T2D, the relationship between leptin and T2D has being extensively studied." (PMID 32824322, 2020). "In addition, receptors for Leptin have been found in testicular tissue and studies have shown that Leptin can directly inhibit gonadotrophic actions on Leydig cells thus further exacerbating testosterone deficiency and therefore obesity." (PMID 32636807, 2020). "Indeed, most models of diet-induced obesity in rodents have presented evidence that obesity causes central and peripheral leptin resistance whereby anorexigenic/orexigenic neurons fail to signal satiety in response to high circulating leptin." (PMID 32729763, 2020). "It has been shown that obesity is associated with increased serum leptin concentrations." (PMID 32927680, 2020). "Obesity is linked with an increase in leptin concentration and a decrease in adiponectin levels." (PMID 33511131, 2020). "Moreover, overexpression of leptin and phosphorylated ObR is implicated in gastric cancer, and diet-induced obesity causes precancerous lesions in the mouse stomach." (PMID 33167521, 2020). "For the two hLepR mutants, L372A and A409E, which have been identified as monogenic causes of early‐onset obesity due to defective leptin signaling, H6 could readily interact and activate both of these mutant receptors." (PMID 32832353, 2020). "As human obesity is associated with impaired appetite control, this implies that other factors may influence the anorexic effects of leptin." (PMID 32729763, 2020). "Hence, we herein add to the current evidence that the harmful effects of maternal hyperglycemia on offspring adiposity and obesity risk is likely to include epigenetic dysregulation of the leptin gene pathway." (PMID 31947745, 2020). "That is why leptin is now considered one of the adipokines responsible for the inflammatory state found in obesity that could predispose to GDM." (PMID 32630697, 2020). "Moreover, LEPR is present in atherosclerotic lesions, and ob/ob mice, which are leptin deficient, are protected from atherosclerosis in spite of obesity." (PMID 32824322, 2020). "Hmga2−/− mice show a reduction in fat tissue, due to lower proliferation of pre-adipocyte cell precursors; significantly, Hmga2 expression is reactivated in adult fat tissue of wild type mice upon high fat diet, and in leptin-deficient genetic models of obesity." (PMID 31963852, 2020). "Therefore, the association of leptin to obesity and inflammation led to the belief that obesity itself plays a role in inducing IFP adipocyte inflammatory propagation and accelerated KOA progression." (PMID 32850724, 2020). "Leptin, a hormone produced by adipocytes, is elevated in individuals with obesity and may mediate the association between obesity and pregnancy outcomes." (PMID 32313676, 2020). "In this study, our aim is to see the association of leptin with obesity and insulin resistance." (PMID 33489589, 2020). "High levels of leptin and insulin in the blood are associated with obesity." (PMID 33046129, 2020). "Furthermore, miR-34a was found to be upregulated in HFD-induced obese mice and leptin-deficient genetic obese mice, also being significantly elevated in obesity-induced liver steatosis patients." (PMID 32962281, 2020). "In obesity, serum leptin is usually associated with increasing adipose depots." (PMID 32093272, 2020).
Obesity (continued). "In this manner, leptin contributes to onset of obesity associated hypertension." (PMID 33171610, 2020). "It was shown that any disorders related to the regulation of these genes may contribute to the development of obesity due to the important role of these genes in hunger regulation (leptin), glucose transport (Glut 4), and insulin susceptibility (adiponectin)." (PMID 32463311, 2020). "Candidate obesity genes and traits associated with obesity include LEP, MCR4, POMC, and PCSK1." (PMID 33113859, 2020). "This mutation is phenotypically manifested as obesity with high leptin levels in the blood." (PMID 32920548, 2020). "It has been speculated that the leptin pathways are supposed to mediate the obesity-associated impairment of chemotherapeutic responses." (PMID 33008429, 2020). "The high plasma leptin levels found in gestational diabetes may be potentiated by leptin resistance at a central level, and obesity-associated inflammation plays a role in this leptin resistance." (PMID 32630697, 2020). "According to the available evidence, dietary SFA increase the risk of obesity, which may result in changes in leptin concentrations." (PMID 32927680, 2020). "LEP promotes wound healing but LEP resistance, associated with obesity, may contribute to the pathophysiology of impaired wound repair." (PMID 33316917, 2020). "Furthermore, low serum zinc level is associated with an elevated level of circulating leptin which causes leptin resistance in obesity due to impairments in the leptin-signaling pathway." (PMID 33138134, 2020). "Moreover, there is growing evidence that leptin resistance can be partly attributed to obesity-associated hypothalamic inflammation." (PMID 33088334, 2020). "However, changes in adipokine secretion have also been linked to resistance; leptin, which is increased in obesity, stimulates proliferation of multiple myeloid cells and activates AKT, which is linked to reduced anti-tumor capacity of chemotherapy." (PMID 31979312, 2020). "On the other direction, chronic inflammation, either from autoimmune or infectious diseases, or impaired microbiota (dysbiosis) may impair the leptin response inducing resistance to the weight control, and therefore it may be a cause of obesity." (PMID 32824322, 2020). "Similarly, the VMH has been identified as a key reaction site for leptin, VMH specific SF-1 knockout mice display leptin resistance and are susceptible to diet-induced obesity." (PMID 33071984, 2020). "An increase in leptin and inhibition of adiponectin levels are both associated with obesity." (PMID 32397362, 2020). "Whether enhancing leptin sensitivity in the context of common obesity, which is associated with elevated leptin levels, may be clinically beneficial, is the subject of much debate." (PMID 30979869, 2019). "Whether the effects of WD consumption on leptin sensitivity or availability occur as a cause or an effect of obesity also remains to be elucidated." (PMID 30814963, 2019). "After stratification by OA status, BMI was significantly associated with LEP promoter methylation only in osteoarthritic individuals; obesity was significantly associated with higher levels of LEP promoter methylation in osteoarthritic individuals (β = 0.03696; p-value = 0.0187)." (PMID 31878053, 2019). "Furthermore, brain specific deletion of MyD88 (myeloid differentiation factor), a downstream mediator of TLR4 signaling, in mice also prevent HFD-induced obesity and associated leptin and insulin resistance." (PMID 30906281, 2019). "It was also reported that higher expression of the leptin gene, associated with higher histone or DNA methylation, was reported to be induced by maternal high-fat diet exposure and to be involved in the transgenerational obesity." (PMID 31849831, 2019). "Interestingly, this study also showed that supplementation of folic acid potently ameliorates obesity-associated reduction in LEP methylation." (PMID 31408957, 2019).
Obesity (continued). "Likewise, common polymorphisms in the LEPR gene have been less consistently associated with plasma leptin levels and obesity phenotypes, depending on the type of population analyzed." (PMID 31766143, 2019). "However, despite their massive obesity, the physiology of leptin-deficient children also entails starvation in the midst of plenty." (PMID 30357355, 2019). "Obesity is associated with increased blood pressure and high levels of leptin." (PMID 31467596, 2019). "Thus genetic screening of consanguineous families with severe early-onset obesity, constitutes a powerful method of identifying causal homozygous mutations and has enabled the identification of rare damaging variants in e.g. LEP, LEPR and MC4R." (PMID 31488071, 2019). "Leptin is associated with obesity, which is a risk factor for OSA." (PMID 31372721, 2019). "The adipocyte-secreted hormone, leptin, stimulates Th1 proliferation and inhibits Treg cell function and, therefore, could be an important effector of obesity-based immune dysfunction, thereby increasing cancer risk." (PMID 31528182, 2019). "Furthermore, this is the first report that highlights an association between polymorphisms in CXCL12 rs501120 and LEP rs7799039 with T2D in Mexican Mestizo adults with obesity." (PMID 30764545, 2019). "Obesity is frequently associated with high serum levels of leptin." (PMID 31052312, 2019). "To determine whether GIO also results in the depression-like phenotype, we conducted the behavioral tests with the leptin-deficient mice (ob/ob), which develop obesity from the third week of age even when maintained on an ND." (PMID 31076569, 2019). "An unbalance of bacterial species was reported in Leptin deficient mice (Lepob/ob), a genetic model of obesity, IR and NAFLD, which had enhanced Firmicutes and lower Bacteroides levels, alterations that have been associated with obesity and subsequent chronic liver diseases." (PMID 31689910, 2019). "The role of leptin in the regulation of energy homeostasis was demonstrated by observing leptin-deficient patients, who develop hyperphagia and obesity during childhood, and can be aided by leptin replacement therapies that suppress appetite and increase energy expenditure." (PMID 31717265, 2019). "Association of adiponectin, leptin, and resistin with inflammatory markers and obesity in dementia." (PMID 31969813, 2019). "Many different models have been used to address mechanisms for how obesity and metabolic disease causes cardiac remodeling and HF development, including leptin or leptin receptor deficient mice and mice with pharmacologically induced (e.g., streptozotocin) diabetes." (PMID 31379826, 2019). "Causes of obesity can be environmental—such as diet composition, overconsumption, and physical inactivity; or genetic—such as having a genetic mutation in the genes encoding the satiety hormone leptin or its receptor." (PMID 31134094, 2019). "Third, it is noteworthy that obesity is associated with various adipokines besides leptin." (PMID 31506433, 2019). "Leptin deficiency leads to extreme obesity and presents the most popular form of monogenic obesity." (PMID 30875721, 2019). "Leptin acts as an energy status signal to reduce food intake and body weight during times of nutritional abundance, whereas mutation of leptin or LepRb results in severe hyperphagia, decreased energy expenditure, and early onset obesity in humans and rodents." (PMID 31057368, 2019). "For instance, in Wistar National Institute of Nutrition (WNIN) obese mutant rats, LEP methylation levels, and transcription levels were positively correlated, suggesting a complex and dynamic underlying epigenetic mechanism for aberrant LEP expression in obesity." (PMID 31878053, 2019). "Last, we could not measure other obesity-associated adipokines such as other obesity-associated adipocytokines such as TNFα, leptin, IL6, IL8, MCP1, and FABP4 because of the limited quantity of samples." (PMID 32117043, 2019).
Obesity (continued). "These associations and possible mechanisms of the deficiencies' metabolic effects, such as their influence on leptin and insulin metabolism, need further studies to help clarify the roles of the different micronutrient deficiencies with respect to obesity and its comorbid conditions." (PMID 31598578, 2019). "These contradictory findings on leptin may be partly explained by leptin resistance due to obesity, which is generally known to be associated with an increase of LAD, LVM, wall thickness, and diastolic dysfunction." (PMID 31703113, 2019). "In their study, women with PE were characterized by overweight and obesity, so the authors have concluded that leptin could be a possible mediator of the association between overweight and obesity and preeclampsia." (PMID 31737362, 2019). "However, another study showed that leptin prevents the obesity-associated inflammatory state and the increased oxidative stress in leptin-deficient ob/ob mice." (PMID 31739649, 2019). "High leptin levels lead to the decrease of testosterone levels caused by obesity in murine." (PMID 31591291, 2019). "Moreover, since periodontitis is linked with obesity, we also incubated periodontal fibroblasts with the proinflammatory adipokines leptin and visfatin, whose plasma levels are increased in obese individuals." (PMID 30609928, 2019). "Finally, LEP rs7799039 has been associated with higher levels of serum leptin and adipose tissue leptin secretion rate, obesity, and hypertension." (PMID 30764545, 2019). "Definite association of obesity with various types of tumors readily drew attention towards its flag bearer hormone leptin (LEP), as it is the humoral mediator through which adipose tissue could exert a direct effect on other organs and processes." (PMID 31592340, 2019). "It is important to emphasize that the increase of these cytokines, such as leptin and IL-6, establishes a pathophysiological link between increased adiposity and obesity-associated cardiovascular disease, insulin resistance, type 2 diabetes, hypertension, and dyslipidemia." (PMID 31489938, 2019). "Yet, since adipocytes are its major source, and given that obesity is usually associated with hyperleptinemia, local concentrations of leptin in adipose tissue may be very high." (PMID 30676227, 2019). "Moreover, PAQR3 levels modulate leptin signaling in mouse models, and leptin is found to mediate the increase in blood pressure associated with obesity." (PMID 30786239, 2019). "It is now confirmed that the dysregulation of central neural circuits is one of the main causes of obesity, which may be the result of the lack or the absence of Leptin signaling caused by LEP gene mutations." (PMID 31871931, 2019). "Leptin-resistance associated with obesity might, though, be prompting the related blood pressure increase." (PMID 30642114, 2019). "Obesity is associated with leptin resistance and rising blood leptin levels while central leptin exposure may be limited." (PMID 31222048, 2019). "Furthermore, we must point at the fact that this is the first report where polymorphisms CXCL12 rs501120 and LEP rs7799039 are associated with T2D in subjects with obesity." (PMID 30764545, 2019). "We detected a novel mutation Leptin mRNA (NM_000230.2): c.350G>T (p.C117F) in the severe obese sisters, speculating that this homozygous mutation in their LEP gene to be causal to their monogenic obesity." (PMID 31067764, 2019). "Although elevated leptin level is a high-risk factor for endometrial cancer, whether it is the most critical molecule associated with obesity and endometrial cancer warrants further investigation." (PMID 31440472, 2019). "In this communication, we report a novel homozygous missense mutation [NM_002303.3], c.350G>T [p.C117F] in LEP associated with very low serum leptin concentrations, hyperphagia, and early-onset obesity in two severely obese sisters from Colombia born from consanguineous parents." (PMID 31067764, 2019).
Obesity (continued). "Notably, few cases of human obesity can be accounted for mutations in leptin or the leptin receptor." (PMID 30823474, 2019). "Here, we reveal that the reason for the prebiotic inulin alleviating obesity-related glucose and lipid metabolism disorders in leptin gene deficiency mice may be closely related to the restoring of certain metabolism-related pathways." (PMID 31026583, 2019). "Moreover, this adipokine is expressed in the fetal side of the placenta greater than in the maternal side, being associated with a higher level of leptin promoter methylation and with a lower expression of the leptin receptor in pregnant women with obesity." (PMID 31794592, 2019). "Leptin and adiponectin are adipocytokines hypothesized to be related to fetal, infant, and child growth, as well as obesity risk." (PMID 32885129, 2019). "Thus, leptin or the leptin receptor-deficient mice display common features of the immuno-metabolic dysfunction that are observed in obesity and diabetes mellitus." (PMID 31032262, 2019). "Zn deficiency and obesity can lead to leptin resistance which may increase NPY levels in the hypothalamus of rodents and men." (PMID 31827626, 2019). "As expected, leptin is associated with gender and BMI because it is a hormone that inhibits hunger and helps regulate energy balance, and this protein is often elevated in those with obesity." (PMID 31466396, 2019). "Resistance to leptin and/or dysfunctions in the leptin system may contribute to this risk as it is well established that obesity is due to development of leptin resistance." (PMID 28819795, 2019). "Genetic deficiency of leptin or its receptor causes hyperphagy and obesity." (PMID 31656948, 2019). "Then, we will address the molecular mechanisms by which obesity-associated changes may affect breast malignancy, and we will outline the role of the obesity cytokine leptin in this type of cancer, discussing both clinical and basic research evidence." (PMID 30634494, 2019). "These patients had rapid reduction in hunger and food intake followed by sustained loss of excess adipose mass, raising hopes that leptin therapy might also be effective in humans with typical obesity." (PMID 30357355, 2019). "Finally, Intestinimonas and Sphingomonas, observed here to increase in the ileum and jejunum, respectively, have both been previously associated with obesity and defective leptin signaling in rat models of obesity." (PMID 31848310, 2019). "Genetic predisposition scores (GPS), particularly consisting of leptin-related SNPs (GPSleptin), were robustly associated with baseline overweight/obesity in children who slept ≤8 h/day (P < 0.001), whereas the association was ablated in those who slept ≥10 h/day (P > 0.05)." (PMID 31285522, 2019). "Leptin is an important adipokine encoded by the obesity gene." (PMID 31440472, 2019). "In WNIN obese mutant rats, LEP methylation levels and transcription were positively correlated, suggesting a complex and dynamic underlying epigenetic mechanism for aberrant LEP expression in obesity." (PMID 31878053, 2019). "In humans, high leptin is associated with cardiac hypertrophy and obesity." (PMID 31242268, 2019). "Recently, among adipokines (i.e., cytokines associated with chronic inflammatory state and obesity) such as leptin, adiponectin, and resistin, only the serum level of resistin was found to be related strongly to the severity of pain in the patients undergoing laparotomy." (PMID 31258474, 2019). "Here, we investigated the role of the obesity hormone leptin, a well-known adipokine implicated in mammary tumorigenesis, on the mechanisms regulating exosome biogenesis and release in both estrogen receptor α (ERα)—positive MCF-7 and triple-negative MDA-MB-231 breast cancer cells." (PMID 31336913, 2019).